IFNG (interferon gamma)
Diseases named in the same sentence as IFNG in open-access papers (continued):
Sharing a sentence is not in itself a finding about the gene and the disease.
infection (continued). "In vivo post challenge studies showed acute simultaneous expression of granzyme A and IFNγ in both type of infections in a tissue specific manner." (PMID 23409078, 2013). "IFNG up-regulation has been demonstrated in duck PBMC in response to a duck-origin H11N9 LPAIV infection." (PMID 23521892, 2013). "It was notable these authors observed reduced inflammatory cytokine production in the lungs of pDC depleted mice at the innate stage of infection, notably IFNγ, the cytokine which is critical for control of infection Cpn infection." (PMID 24386207, 2013). "The results of animal studies of genital chlamydial infection suggest that resolution of infection is dependent on a Type-1 CD4+ T-helper lymphocyte (Th1) response-mediated primarily through IFNγ." (PMID 23457650, 2013). "The levels of interleukin-6 (IL-6) and interferon-gamma in the bronchoalveolar lavage fluids after infection were significantly decreased in offspring mice exposed to methamidophos." (PMID 24369005, 2013). "TLRs function in innate immunity as sensors of microbial PAMPs or other ligands, and their expression is regulated by these molecules and also by IFNγ, a proinflammatory cytokine produced in response to infection." (PMID 23460923, 2013). "Using Leishmania major infection to test the biological significance of changes in IL-4, we found that blocking IL-4 during infection also led to an increased number of IFNγ-producers in the infected dermis and improved pathogen control." (PMID 23991011, 2013). "The type II interferon IFNγ plays an important role during the immune response to bacterial pathogens, but is also induced upon infection with viruses." (PMID 23941132, 2013). "Previous studies have indicated that Toxoplasma pre-infection reduces GAF formation in IFNγ-treated cells." (PMID 23527309, 2013). "Several human studies point to the importance of the CMI response to ocular Ct infection, although direct longitudinal evidence that resolution is IFNγ-dependent is limited." (PMID 23457650, 2013). "Treatment with the positive control IFNγ or infection with the parasite strain RH (Tg) induced significant STAT1 binding activity." (PMID 23527309, 2013). "One month after confirmed CA/09 infection, TNFα, IFNγ, and IL-2 responses against all peptide pools were higher in comparison to the unexposed cohort, and most of these increases were significant." (PMID 23526940, 2013). "The cells were differentiated by PMA treatment and stimulation with interferon gamma for 24 h prior to infection." (PMID 23862148, 2013). "The tools most commonly used for diagnosis of latent M. tuberculosis infection are the tuberculin skin test and the newer interferon-gamma release assays, both of which rely on an antigen-specific memory response as an indicator of infection." (PMID 23738853, 2013). "The innate immune response, through pro-inflammatory cytokines such as IFNγ, is thought to contribute to the initial control of parasitaemia following infection by P. falciparum, but to also correlate with development of clinical symptoms." (PMID 23437368, 2013). "IL-10−/− mice were shown to have similar bacterial loads in the lung and enhanced levels of IFNγ production during early infection compared to wild type control mice, though the elevated IFNγ failed to provide any additional protection." (PMID 24350246, 2013). "The production of IFNγ characterises the Th1 response and has several antichlamydial actions, which probably play a central role in clearing infection." (PMID 23457650, 2013). "On the contrary, WSX-1−/− mice generate more IFNγ-producing CD4+ T cells than wild-type mice after infection with Toxoplasma gondii, indicating that IL-27 signal is not necessary for the generation of Th1 immunity to the infection." (PMID 24068935, 2013).
infection (continued). "Antigen-specific T lymphocytes that migrate to the infection site will multiply within the early lesions or tubercles and release proinflammatory cytokines such as IFNγ which in turn activates macrophages to kill the intracellular mycobacteria." (PMID 24350246, 2013). "In contrast, pre-infection with Toxoplasma resulted in blockage of IFNγ-mediated binding while infection alone resulted in little to no binding." (PMID 23527309, 2013). "These chemokines recruit NK cells at the infection site where IL-12 and IL-18 promote IFNγ production which then exerts protective immune response." (PMID 24350246, 2013). "It is likely that the IFNγ test measured these true positives, possibly at an early stage of infection." (PMID 24308747, 2013). "The release of interferon-gamma (IFN-γ) by T lymphocytes increases at a localized site of infection with Mycobacterium tuberculosis antigen." (PMID 24386296, 2013). "IFNγ and TNFα production by PBMCs is of pivotal importance in generating an appropriate bactericidal response to infection." (PMID 23935244, 2013). "Blocking of IL-10R signaling with anti-IL-10R monoclonal antibody during chronic infection boosts T-cell recruitment in the infection site and increases T-cell mediated IFNγ production, thereby providing enhanced protection with reduced bacterial loads." (PMID 24350246, 2013). "Further interesting detail can be observed when we allow our simulations to run up to 24 h post infection or post IFNγ treatment." (PMID 22664637, 2013). "When CD11c+ cells were depleted, the upregulation of IL-12p40 and IFNγ resulting from the infection was severely impaired." (PMID 24367259, 2013). "We examined the mucosal inflammatory response in post-infective mouse intestines and identified increased phagocytic infiltration and activation as well as IFNγ and IL-8 production during infection, which persisted into the post-clearance phase." (PMID 23991642, 2013). "The inflammatory response to infection is shaped by alterations in splenic cytokine production, particularly IFNγ, which differs after intragastric versus intraperitoneal infection." (PMID 23840314, 2013). "As expected, intravenous infection with live Lm-Ova induced a high percentage of IFNγ-producing CD4+ T cells." (PMID 24068935, 2013). "IFNγ application as a pretreatment and during infection (b/a stimulation) was able to reduce IAV replication in human neutrophils." (PMID 24171176, 2013). "In infectious disease mouse models, DN T cells produce IL17 early during pulmonary Francisella tularensis live vaccine strain infection and also secrete IFNγ necessary for controlling intracellular bacterial growth." (PMID 23825945, 2013). "The fact that Mtb upregulates miR-29 expression during the course of the infection suggests that it also modulates IFNγ production to tilt the immune response in its favor." (PMID 23760605, 2013). "This local activation was then followed by a Th1 mediated IFNγ expression, consistent with the single infection model." (PMID 22253585, 2012). "Airway levels of CXCL1, CCL2, CCL3, CCL5, IFNγ, IL-6, and TNFα were measured 3 and 6 days after infection." (PMID 22496659, 2012). "At day 7 post-infection, IFNγ and TNFα were significantly more elevated in cecal and blood, respectively, in A2AAR-/- mice than wild-type mice indicating that onset and resolution of inflammation were both delayed in the absence of A2AARs." (PMID 23217055, 2012). "In humans, destructive forms of cutaneous leishmanasis are associated with higher frequencies of CD8 cells and high levels of IFNγ in lymph node tissue as well as at the site of infection." (PMID 23028548, 2012). "To further show that secretion of IFNγ is impaired in CD4+ T cells during infection, we measured STAT1 phosphorylation in dLN CD4+ T cells of L. major-infected N1N2ΔCD4Cre mice." (PMID 22396647, 2012). "Authors suggest that TLR9 has a primary role in the MyD88-dependent induction of IL12/IFNγ synthesis during infection." (PMID 21869919, 2012).
infection (continued). "Here we describe the unexpected mutual requirement for both host-derived IFNγ and infection-dependent stimulation of an RNA-sensing pathway in order to mediate the inhibition of a cytosolic bacterial pathogen." (PMID 22912573, 2012). "At any time point of infection, the relative proportions of IFNγ-producing P261–269-specific CD8+ T-cells remained lower than that of P261–269 tetramer-stained cells." (PMID 22940382, 2012). "It has generally been believed that the early immune response to infection with MAP consisted primarily of a cellular immune response characterized by interferon gamma production, and this response would later be replaced by antibody production." (PMID 22792514, 2012). "The suppression of Th1 cell proliferation acts both on the inductors and effectors and is mainly driven by the repression of the IFNγ mediated inflammatory activity during the early stages of the infection." (PMID 22253585, 2012). "Here, using mice with ablation of Notch in their T cells, we demonstrate that expression of either N1 or N2 on T cells is necessary and sufficient for the differentiation of IFNγ-secreting Th1 cells and the consequent control of infection." (PMID 22396647, 2012). "Mavs−/− mice and IFNγ−/− mice harbored bacterial burdens that were nearly 1 log greater than those observed in Mavs-sufficient mice by day 1 post-infection." (PMID 22912573, 2012). "Stat1-deficient mice succumb to Lm during the early, innate phase of infection, strongly suggesting a dominant role for Stat1 in IFNγ-mediated macrophage activation." (PMID 22719255, 2012). "Ad-IFNγ infection resulted in antiproliferative effects on NPC cells by inducing G1 phase arrest and cell apoptosis." (PMID 23272637, 2012). "In our study, although no increase of CD4+ and CD8+ T cells count was observed, a significant increase of IFNγ, with peak on day 10 after infection, was observed infecting the animals with DENV-1 strain Mochizuki with a lower viral dose (7.2 × 107 PFU)." (PMID 22666132, 2012). "In this study we provide evidence that Treg cells can be attributed as a major regulatory subtype preventing excessive production of IFNγ and reducing local inflammation after infection in CCR6−/− mice." (PMID 23028548, 2012). "Increased protection correlated with an increased percentage of TB10.4 specific IFNγ/TNFα/IL-2 or TNFα/IL-2 producing CD4 T cells at the site of infection." (PMID 22768165, 2012). "It is still unclear why we observe a higher level of IFNγ induced phospho-STAT1Tyr after pre-infection with any strain of Toxoplasma." (PMID 23240025, 2012). "We did observe that the most severe impairment of IFNγ secretion at enrollment was correlated with either development of secondary infection or death." (PMID 22742734, 2012). "IFNγ-producing CD4+ T cells are recruited to this site during challenge infection potentially mediating parasite killing via classical activation of macrophages producing iNOS via an IFNγ and TNFRI-dependent pathway." (PMID 22360486, 2012). "Proper IFNγ signaling is also required in vivo for a normal immune response to infection with Listeria monocytogenes (L.m.)." (PMID 23115618, 2012). "This increased resistance against infection was characterized by augmented levels of bactericidal factors and inflammatory cytokines: ROS, NO, IFNγ TNF IL-6 and IL-12." (PMID 22629382, 2012). "We therefore analyzed the amount of IFNγ in the spleen and found that administration of MSCs led to a 1.3-fold increase in its production after infection (p = 0.027 vs. PBS-CVB3)." (PMID 22815907, 2012). "Although continued IFNγ-mediated gene induction would also be blocked following CHX treatment, the robust expression of IFNγ-dependent, infection-independent genes would have been strongly upregulated prior to treatment with CHX." (PMID 22912573, 2012). "In B6.CCR6−/− mice increased capability of CD8 cells to produce IFNγ also correlated with higher levels of IL12p40 expression at the peak of infection." (PMID 23028548, 2012).
infection (continued). "IFNγ has been shown to induce effects resulting in heightened immune surveillance and immune system function during infection and to promote M1 macrophage polarization and activation." (PMID 23185575, 2012). "IFNγ production in the NK cells of infected mice was assessed after five hours of infection by staining for intracellular IFNγ in DX5+ cells." (PMID 22912878, 2012). "IFNγ and TNFα levels were increased during infection in wild-type mice at both days 3 and 7 post-infection." (PMID 23217055, 2012). "Following the infection, IFNγ rapidly peaked after two time steps while IL4 and IL10 activation followed with a delay, in line with empirical findings." (PMID 22253585, 2012). "Elevated levels of IFNγ mRNA has been found in the spleen and bone marrow during the acute phase of infection." (PMID 22912637, 2012). "We chose L.m. for these experiments because protective immune responses to infection act substantially via IFNγ signaling." (PMID 23115618, 2012). "But, our microarray data from the murine macrophage RAW264.7 cell line shows that pre-infection with RH(I) parasites can still inhibit IFNγ induced Socs1 transcript by two-fold." (PMID 23240025, 2012). "An intact IFNγ pathway is essential to combat infection initiated from a wide range of microbial pathogens; therefore patients with genetic defects in Stat-1 signaling are susceptible to microbial infections." (PMID 22253910, 2012). "While splenocytes from 5 week-infected cotton rats produced more IFNγ inresponse to SEB than uninfected animals, by 11 weeks of infection IFNγ production fromsplenocytes had decreased compared to 5 weeks." (PMID 23285308, 2012). "IFNγ release assays (IGRAs) are therefore very important tools for measuring the immune response to M. tb infection (including diagnosis of infection) and for monitoring the impact of vaccination." (PMID 24710359, 2012). "This differs from increase of serum levels of IL-4, IFNγ and IL-12 observed in CcS/Dem strains after 8 weeks of infection." (PMID 22679519, 2012). "Possibly IFNγ contributes to protective CTL memory when infection occurs with a high infectious dose." (PMID 22719255, 2012). "T cells recruited to the infected lung are thought to control infection by producing interferon gamma (IFN-γ) in response to mycobacterial antigens presented by macrophages." (PMID 22363214, 2012). "Our data highlight the importance of and requirement for IFNγ-activated macrophages for clearance of the pathogen during early phases of infection, and show a yet unanticipated detrimental role for T cell Stat1." (PMID 22719255, 2012). "We first blotted for IRF1 as a control to confirm that infection with any of these strains inhibited the IFNγ induced accumulation of IRF1, as we have shown by immunofluorescence." (PMID 23240025, 2012). "As expected, the genes encoding IFNγ and IL2 cytokines, two biomarkers of infection, were significantly upregulated in the infected group." (PMID 22815916, 2012). "During the course of infection, natural killer (NK) cells contribute to innate immunity by producing cytokines, particularly interferon-gamma (IFN-γ)." (PMID 23098236, 2012). "A2AAR-/- and littermate wild-type (WT) mice were similarly infected, and IFNγ and TNFα were measured at peak of and recovery from infection." (PMID 23217055, 2012). "After two hours of infection with either RH or RHΔrop16 parasites, HFFs were subsequently stimulated with IFNγ for two hours, cells were fixed and permeabilized, and IRF1 expression and STAT1 tyrosine phosphorylation were visualized." (PMID 23240025, 2012). "Inflammatory environments with low IFNγ levels, such as at the beginning of an infection, can facilitate the immunostimulatory properties of MSCs, such as antigen presentation." (PMID 22815907, 2012). "Dendritic cells also activated the Th2 cell mediated expression of IL4 and as this arm of the immune response developed, IFNγ decreased although remained in an active state throughout the infection." (PMID 22253585, 2012).
infection (continued). "The accumulation of IFNγ+ cells preceded the entry of Pfn+ cells into the cardiac tissue during acute infection." (PMID 22532799, 2012). "One study to date has demonstrated iNKT cell culture supernatant inhibition of HIV p24 production during in vitro CD4+ T cell infection, which was shown to be IFNγ-dependent." (PMID 22916008, 2012). "The majority of studies have demonstrated that interferon gamma (IFN-γ) plays an important role in the clearance of DV following infection." (PMID 23121866, 2012). "Relatively high levels of TNFα, IFNγ, IL-1, IL-6 were recorded at the early stage of infection and persisted throughout." (PMID 23323093, 2012). "As shown after low dose infection with L. major, enhanced IL-4 expression is followed by a compensatory IFNγ response by CD8 cells." (PMID 23028548, 2012). "Recently, the antigen-specific ex vivo induction of interferon gamma (IFN-γ) had been used to detect infection with M. tuberculosis." (PMID 22701501, 2012). "This lytic activity was further enhanced by infection of cells with an Ad vector expressing murine IFNγ." (PMID 23056548, 2012). "This will have suppressed IFNγ, resulting in the enhancement of bacterial intensity and deferred clearance in the lower respiratory tract compared to single infection." (PMID 22253585, 2012). "Infection with any of these strains significantly inhibited IFNγ induced luciferase activity, and the extent of this inhibition did not vary significantly between the strains." (PMID 23240025, 2012). "We investigated IFNγ expression at protein levels in CNE-1, CNE-2 or C666-1 infected by Ad-IFNγ, and found that IFNγ protein concentration in the supernatants of NPC cells continuously increased within 72 hours post-infection." (PMID 23272637, 2012). "As the infection proceeded, and consistent with our empirical work, IFNγ and IL10 expression rapidly peaked and then slowly decreased below the threshold through the course of the infection." (PMID 22253585, 2012). "CD8+ T-cells mediate protection against infection through the secretion of cytokines, such as IFNγ and tumor necrosis factor (TNF), and through CTL activity via the release of cytotoxic granules containing granzymes, granulysins and Pfn." (PMID 22532799, 2012). "While unstimulated MEFs were highly permissive for S. flexneri replication over a 15 hour infection, pre-stimulation of MEFs with IFNγ prior to infection drastically inhibited bacterial growth by 15 hours post infection (hpi)." (PMID 22912573, 2012). "Since we predominantly found LMP2/MECL-1/β5 proteasomes in IFNγ-stimulated lmp7−/−Mefs in vitro, we wondered to which extent these mixed proteasomes were formed following infection of lmp7−/− mice in vivo." (PMID 22768135, 2012). "In contrast, mRNA levels of cytokines Ifnγ and Tnfα peaked late during infection on day 7, a time where animals showed signs of acute disease." (PMID 22911267, 2012). "We examined associations between the magnitude and breadth of the pre-infection IFNγ ELISpot response (within and across proteins) and each epitope-based distance measure in the 32 vaccine recipients with pre-infection T-cell response and sequence data." (PMID 22952672, 2012). "Similar responses were also obtained post-treatment with interferons, indicating the possibility of a common pathway for infection response and long non-coding RNA regulation mediated through the interferon gamma involved immunological pathways." (PMID 23316211, 2012). "The frequency of IFNγ-producing CD8 cells was higher in B6.CCR6−/− compared to B6.WT mice as seen already in the early phase of infection." (PMID 23028548, 2012). "After infection, both bacteria produced endotoxins and various cytokines released by activated monocytes/macrophages such as TNFα, IL1β, IFNγ etc. can promote HMGB1 translocation from nucleus to cytoplasmic organelles." (PMID 22947457, 2012).